JAK2 (Janus kinase 2)
Diseases named in the same sentence as JAK2 in open-access papers (continued):
Sharing a sentence is not in itself a finding about the gene and the disease.
heart failure (10 papers, 2013 to 2026). Inability of the heart to pump blood at an adequate rate to meet tissue metabolic requirements. "The underlying mechanisms by which CHIP and its mutations in ASXL1, DNMT3A, TET2, or JAK2 are related to heart failure development and progression are not well understood." (PMID 35657494, 2022). "Aberrant activation of the JAK2/STAT3 pathway is associated with myocardial fibrosis and heart failure." (PMID 40290189, 2025). "Studies have also reported that captopril exerted a cardioprotective effect on heart failure by inhibiting phosphorylation of JAK2/STAT3." (PMID 31619994, 2019). "Taken together, the high expression and activation of IL7Rα, PI3K/Akt, and Jak2/STAT5, we infer that the IL7 signaling pathway is activated in macrophages within the granuloma of patients with heart failure." (PMID 40521183, 2025). "Previous studies showed that STAT1 expression was increased in DOX-induced rat cardiomyocytes, and inhibition of STAT1 gene expression or JAK2/STAT1 signaling pathway reduced DOX-induced ferroptosis and myocardial fibrosis in rat cardiomyocytes, thereby alleviating heart failure." (PMID 39243097, 2024).
inflammatory bowel disease (10 papers, 2016 to 2024). A spectrum of small and large bowel inflammatory diseases of unknown etiology. "Inflammatory bowel disease (IBD) is intricately linked to dysregulated immune responses within the gastrointestinal tract, where the JAK2/STAT3 pathway assumes a pivotal role." (PMID 39187810, 2024). "Intervention with AG490 (a highly selective JAK2 inhibitor) in a rat model of inflammatory bowel disease (IBD) significantly decreased the levels of IL-6 and IL-17A and increased the levels of IL-10, suggesting a protective effect on IBD." (PMID 35590365, 2022). "Interestingly, ER-β agonists have shown to inhibit inflammation in both in vivo and in vitro models of inflammatory bowel disease via downregulation of ERK, JAK2 and STAT, suggesting the general role of estrogen in inflammatory process." (PMID 34681670, 2021). "Background and objective: Abnormal activation of Janus kinase 2 (JAK2) promotes the pathogenesis and progress of inflammatory bowel disease (IBD) by stimulating the cytokine traffic." (PMID 34594215, 2021).
myeloid leukemia (10 papers, 2007 to 2025). A clonal proliferation of myeloid cells and their precursors in the bone marrow, peripheral blood, and spleen. "While evaluating the therapeutic relevance of CARM1 inhibition, we observed the differential sensitivity of AML cell lines and noticed that JAK2-V617F mutation-positive myeloid leukemia cells showed a lower sensitivity to CARM1-inhibition." (PMID 38649367, 2024). "One of the patients with NRAS and JAK2 mutations had myeloid leukemia with a prior described JAK2 mutation." (PMID 39000050, 2024). "Our data provides first evidence that JAK2-mutated cells may show an even greater dependency than other myeloid leukemia cell lines." (PMID 35654819, 2022). "First, we confirmed that HEL cells have the highest level of JAK2 phosphorylation among the various myeloid leukemia cell lines tested, including SET2 cells." (PMID 38649367, 2024). "The dependency of JAK2-V617F mutant AML cells on CARM1 is consistent with our previous studies showing that CARM1 is an essential gene for the growth of myeloid leukemia cells." (PMID 38649367, 2024). "Therefore, using the Jak inhibitor AG490, we investigated if Jak2, in addition to its involvement in drug resistance of myeloid leukemia cells, also contributes to resistance development of lymphoid leukemia cells." (PMID 17958915, 2007).
pulmonary embolism (10 papers, 2020 to 2026). The obstruction of the pulmonary artery or one of its branches by an embolus, sometimes associated with infarction of the lung. "However, one subject with pulmonary embolism was the relative of the variant carrier with the mildly activating JAK2 variant of uncertain significance." (PMID 32397294, 2020). "There was a postpartum pulmonary embolism in a pregnancy with JAK2‐mutated PV, not treated with postpartum LMWH prophylaxis." (PMID 36819152, 2023).
pulmonary hypertension (10 papers, 2018 to 2026). Increased pressure within the pulmonary circulation due to lung or heart disorder. "Collectively, our data suggest that loss of Jak2 in smooth muscle cells confers protection against hypoxia‐induced pulmonary hypertension by attenuating pulmonary vascular remodelling and PASMC hyperplasia." (PMID 31943454, 2020). "Janus kinase 2 (JAK2) was thought to be involved in pulmonary vascular remodeling in pulmonary hypertension." (PMID 36186970, 2022). "During the progression of pulmonary arterial hypertension (PAH), miR-361-5p can promote pulmonary artery smooth muscle cell viability through activating JAK2/STAT3 pathway." (PMID 37328892, 2023).
vitiligo (10 papers, 2023 to 2025). Generalized well circumscribed patches of leukoderma that are generally distributed over symmetric body locations and is due to autoimmune destruction of melanocytes. "JAK inhibitors (JAKi), such as tofacitinib (a pan JAKi) and ruxolitinib (selectivity for JAK1 and JAK2), have apparently reversed vitiligo in some case reports, and ongoing clinical trials." (PMID 37403086, 2023). "The patient was prescribed Opzelura (ruxolitinib) 1.5% topical cream, an inhibitor of the JAK1 and JAK2 proteins prevalent in the immune reaction responsible for vitiligo, as well as tacrolimus 0.1% topical ointment, another immunosuppressant, and was instructed to apply them over the affected area." (PMID 38817459, 2024). "However, FHB therapy significantly hampered the increase of mRNA expression of Jak1, Jak2, Stat1, Stat2, and Stat3 in vitiligo mice, and this inhibitory effect was dose-dependent." (PMID 37575231, 2023). "In vitiligo, for example, IFN-γ produced by CD8+ T cells activates JAK1 and JAK2, leading to further recruitment of CD8+ T cells." (PMID 39161766, 2024). "To further investigate the effect of FHB on the JAK-STAT pathway in vitiligo mice at the transcriptional level, we used qRT-PCR to examine the influence of FHB on the mRNA expression of Jak1, Jak2, Stat1, Stat2, and Stat3 in the lesion region." (PMID 37575231, 2023). "Recent studies indicate that JAK1 and JAK3, but not JAK2, demonstrated higher cutaneous expression in vitiligo skin compared to healthy skin." (PMID 39201060, 2024). "Indeed, in total, our data demonstrated that IFN-γ in the vitiligo lesions stimulates fibroblast’s expression of CCL2 and CCL8 through activating the JAK2/STAT1 signaling pathway." (PMID 36672151, 2023). "JAK1 and JAK2 modulate the transduction signal after IFN-γ binds to its receptor, and as such, the downstream IFN-γ/CXCL10 signaling pathway may be a potential therapeutic target in vitiligo." (PMID 39201060, 2024).
steatosis (9 papers, 2011 to 2023). Increased lipid within the cytoplasm of cells. "In addition, GWAS data collected from patients with NAFLD revealed single nucleotide polymorphisms (SNPs) in 18 different genes in the GH signaling pathway, including Gh, Ghr, Jak2, and Stat5b, are associated with steatosis." (PMID 34685512, 2021). "Similar to GHtgSTAT5Δhep mice, JAK2 deficiency resulted in severe steatosis in the GHtg background." (PMID 27713471, 2016). "We confirm that loss of JAK2 leads to overt hepatomegaly and steatosis." (PMID 27713471, 2016). "Moreover, hepatocyte-specific deletion of JAK2 causes massive steatosis and GH resistance." (PMID 21725989, 2011). "When JAK2L mice are crossbred to a GH-deficient mouse model (lit/lit;) or crossbred to mice with the adipose-tissue knockout of JAK2, steatosis is dramatically reduced." (PMID 34685512, 2021). "The important role of the reciprocal shift in IGF1/GH and subsequent GH-mediated WAT lipolysis to the development of steatosis in these model systems is based on studies in mice with the loss of hepatocyte GHR signaling, due to the congenital liver-specific knockout of JAK2 (JAK2L)." (PMID 34685512, 2021). "However, hepatocyte-specific deletion of JAK2 in mice developed steatosis, whereas the same mice were completely protected against the development of diet-induced steatohepatitis and glucose intolerance." (PMID 33924165, 2021). "The preclinical models of hepatic Jak2 gene deletion reported that hepatic lipid accumulation and steatosis occurred, but without worsening of insulin resistance." (PMID 31719581, 2019). "Consistent with the negative association between GH and steatosis, mouse models with the congenital, liver-specific knockout of the GHR or its downstream effectors (JAK2 or STAT5) as adults exhibit steatosis, glucose intolerance, insulin resistance, and WAT lipolysis." (PMID 34685512, 2021).
type 1 diabetes (9 papers, 2019 to 2025). "A case report showed that JAK1/JAK2 inhibitor ruxolitinib normalized blood-glucose levels and discontinued exogenous insulin in a patient with type 1 diabetes caused by STAT1 gain-of-function." (PMID 35242127, 2022). "DE genes in the PPI networks were also highly connected to type 1 diabetes drug–gene targets, particularly JAK2 and JAK1." (PMID 41306972, 2025). "Differentially expressed genes in the PPI networks were also highly connected to type 1 diabetes drug–gene targets, particularly JAK2." (PMID 41306972, 2025). "The goal of this study is to determine if the JAK1/JAK2 inhibitor baricitinib impairs type 1 diabetes autoimmunity and preserves beta cell function." (PMID 35606820, 2022). "In another patient (Case 3), elevated thrombocytes were initially attributed to type 1 diabetes, and a JAK2-positive ET was delayed for 5 years." (PMID 36654555, 2022). "Enhanced expression of JAK2 specifically in podocytes markedly augmented the DKD phenotype in the present model of type 1 diabetes in mice." (PMID 30763329, 2019). "In summary, we identified sorafenib as an inhibitor of Th1 differentiation and an indirect inhibitor of JAK2 and found that sorafenib prevents and reverses type 1 diabetes in NOD mice by decreasing the accumulation of Th1 cells and the expression of inflammatory cytokines in pancreas." (PMID 35242127, 2022). "The baricitinib in new onset type 1 diabetes (BANDIT) trial, will investigate whether the JAK1/JAK2 inhibitor baricitinib, currently used in the treatment of rheumatoid arthritis and alopecia, can facilitate beta-cell survival in individuals with recent-onset (<100 days) T1D." (PMID 37867531, 2023).
acute GVHD (8 papers, 2018 to 2024). "The findings from this study suggest that the occurrence of the JAK2 haplotypeGGCC_46/1 in both recipients and donors significantly affected the development of acute graft-versus-host disease, confirming that JAK2 polymorphisms may have an influence on cytokines signaling pathways." (PMID 29641446, 2018). "Ruxolitinib, a balanced JAK1/JAK2 inhibitor with similar specificity to baricitinib has been approved for the treatment of steroid refractory acute GVHD and chronic GVHD." (PMID 37744381, 2023). "The JAK1/JAK2 inhibitor ruxolitinib was approved by the US Food and Drug Administration for the treatment of steroid-refractory acute GVHD in mid-2019." (PMID 35908108, 2022). "A recent phase III clinical trial indicated that ruxolitinib treatment, a selective Janus kinase (JAK1 and JAK2) inhibitor, significantly improved glucocorticoid refractory acute GVHD." (PMID 36052066, 2022). "In May 2019, ruxolitinib, a Janus kinase (JAK) 1/JAK2 inhibitor, became the first US Food and Drug Administration–approved treatment for steroid-refractory acute GVHD in patients ≥12 years old." (PMID 35739326, 2022).
Anxiety (8 papers, 2017 to 2026). Intense feelings of nervousness, tension, or panic often arise in response to interpersonal stresses. "The cytokine tumour necrosis factor-α (TNF-α) and its closely associated janus kinase 2 (JAK2)-signal transducer and activator of transcription (STAT3) signalling pathway regulate the neuro-inflammatory response in the brain, thus participating in the development of anxiety." (PMID 28336920, 2017). "In CIS rats, XYS treatment, comparable to the JAK2 inhibitor AG490, alleviated anxiety-like behavior, reduced hippocampal damage, and inhibited activation of the TNF-α/JAK2-STAT3 pathway." (PMID 41535967, 2026). "XYS can downregulate the levels of JAK2, phosphorylated -JAK2 and STAT3 in the hippocampus of rats with anxiety behaviors." (PMID 37046230, 2023). "In contrast, we used a bilateral intracerebroventricular microinjection of AG490, a JAK2-specific inhibitor, to observe the role of the JAK2-STAT3 signalling pathway in CIS-induced anxiety-like behaviours in this study." (PMID 28336920, 2017). "Paradoxically, inhibiting the Janus kinase 2 (JAK2)/STAT3 pathway in reactive astrocytes does not alter tau or Aβ pathology but modulates anxiety-related behaviors, indicating pathway-specific effects." (PMID 40384856, 2025).
dyslipidemia (8 papers, 2011 to 2024). "In the univariate analysis, there were gender differences in the whole cohort with regard to disease distribution, age at diagnosis, smoking history, dyslipidemia, median white blood cell count, and median JAK2 V617F allele burden." (PMID 22084670, 2011). "Despite their younger age, less prevalent dyslipidemia or smoking history, lower white blood counts, and a lower JAK2 V617F allele burden, women had higher rates of AVT and had comparable rates of all other vascular complications." (PMID 22084670, 2011). "Despite their younger age, less prevalent dyslipidemia or smoking history, lower white blood counts, and lower JAK2 V617F allele burden, women had higher rates of abdominal venous thrombosis and comparable rates of all vascular complications." (PMID 22084670, 2011). "In this MPN cohort, women were younger at diagnosis, were less likely to have a history of tobacco use or dyslipidemia, and had lower median white blood cell counts and JAK2 V617 allele burdens, compared to men." (PMID 22084670, 2011). "We obtained overlapping genes between Danshen compounds and dyslipidemia, and through a PPI network analysis, key target genes such as JAK2, STAT3, PI3K, AKT1, and TLR4 were acquired." (PMID 39598338, 2024). "The analysis of the association of SNPs with T2DM demonstrated that SOCS3 and JAK2 genes may be associated with T2DM, whereas interaction between the SOCS3, JAK2, and STAT3 are related to metabolic syndrome features." (PMID 36674935, 2023). "Excessive myelopoiesis can be driven by dyslipidemia and cholesterol accumulation in hematopoietic stem and progenitor cells (HSPC) and may involve increased signaling via Janus kinase 2 (JAK2)." (PMID 32086626, 2020).
fibrosarcoma (8 papers, 2012 to 2024). A malignant mesenchymal fibroblastic neoplasm affecting the soft tissue and bone. "We transfected JAK2-deficient γ2A-fibrosarcoma cells expressing IL-23R and IL-12Rβ1 with various amounts of JAK2-encoding constructs and assessed their response to IL-23." (PMID 37875108, 2023). "JAK1 and JAK2, for example, have been implicated in promoting invasion and metastasis in certain cell types such as 2C4 human fibrosarcoma cells, which are highly invasive." (PMID 24089705, 2013). "To test the possibility that βV665A activates STAT1 via JAK2, we first used γ2A fibrosarcoma cells, which lack JAK2 and are therefore unresponsive to interferon γ." (PMID 35689379, 2022). "We further verified this observation by treating matrix embedded fibrosarcoma cells with inhibitors of JAK2 and STAT3." (PMID 30220965, 2018). "We have generated and characterized human fibrosarcoma (γ2ALEPRb/JAK2) that stably expresses LEPRb and JAK2." (PMID 22359610, 2012).
hyperuricemia (8 papers, 2021 to 2025). An abnormally high level of uric acid. "Several studies have shown that the JAK2/STAT3 signaling pathway is involved in hyperuricemia-induced nephropathy and that inhibiting this pathway can improve hyperuricemia-induced renal injury and fibrosis." (PMID 40361044, 2025). "Previous studies have implicated the JAK2/STAT3 signaling pathway and downstream IL-6 in uric acid-induced kidney injury, highlighting potential strategies for preventing and treating hyperuricemia-associated kidney damage." (PMID 40170729, 2025). "This study aimed primarily to elucidate the role of HMGCS2 and the JAK2/STAT3 signaling pathway in hyperuricemia-induced mitochondrial dysfunction." (PMID 40361044, 2025). "Model of hyperuricemia-induced mitochondrial dysfunction and oxidative stress in cardiomyocytes involving JAK2/STAT3/HMGCS2 signaling." (PMID 40361044, 2025). "On the other hand, the Janus kinase 2/signal transducer and activator of transcription 3 (JAK2/STAT3) signaling pathway was inhibited in the liver of the mouse model with hyperuricemia." (PMID 38042879, 2023). "In conclusion, these findings demonstrate that inhibiting the JAK2/STAT3/HMGCS2 signaling pathway with ruxolitinib and S3I-201 alleviates mitochondrial dysfunction, oxidative stress, and cardiac dysfunction caused by hyperuricemia." (PMID 40361044, 2025). "In addition, in vitro, the JAK inhibitor ruxolitinib can alleviate hyperuricemia-induced mitochondrial dysfunction and oxidative stress by affecting the JAK2/STAT3/HMGCS2 signaling pathway." (PMID 40361044, 2025). "Next, we investigated whether JAK2 plays a crucial role in hyperuricemia-induced mitochondrial dysfunction and oxidative stress." (PMID 40361044, 2025). "However, whether hyperuricemia activates the JAK2/STAT3 signaling pathway in cardiomyocytes remains to be further investigated." (PMID 40361044, 2025). "Recent research has demonstrated that hyperuricemia can activate the JAK2/STAT3 signaling pathway in the kidney, thereby contributing to the pathogenesis and progression of hyperuricemia-induced nephropathy." (PMID 40361044, 2025). "And another recent document illustrated that the phosphorylation levels of JAK2 and STAT3 were upregulated in the kidney of hyperuricemia mice." (PMID 36248423, 2022). "Our study revealed that hyperuricemia significantly increased the phosphorylation levels of JAK2 and STAT3 in AC16 cardiomyocytes and myocardial tissue from hyperuricemic mice, whereas the total protein levels of JAK2 and STAT3 remained unchanged." (PMID 40361044, 2025). "Western blot analysis showed that hyperuricemia significantly increased JAK2 and STAT3 phosphorylation in cardiac tissue without altering total protein levels." (PMID 40361044, 2025). "Similarly, treatment with the JAK inhibitor ruxolitinib also significantly lowered the phosphorylation levels of JAK2 and STAT3 induced by hyperuricemia, achieving effects comparable to those of STAT3 knockout." (PMID 40361044, 2025). "Intervention targeting the phosphorylation of JAK2 and STAT3 may inhibit the JAK2/STAT3/HMGCS2 signaling pathway, thereby alleviating hyperuricemia-induced mitochondrial dysfunction, oxidative stress, and energy metabolism disorders, and potentially improving heart dysfunction." (PMID 40361044, 2025).
Immunodeficiency (8 papers, 2012 to 2025). Failure of the immune system to protect the body adequately from infection, due to the absence or insufficiency of some component process or substance. "In summary, we identified that loss of JAK1 in NK cells drives innate immune deficiency, whereas JAK2 deficiency leaves NK cell numbers and maturation unaltered." (PMID 30671064, 2018). "With this consideration, we have noted the presence of rare variants in other immunodeficiency genes (JAK2, JAK3, IL17RA, IL12RB2, CARD14, and TYK2) in our various patients, which could feasibly contribute to the penetrance and/or differences in the clinical phenotypes of the patients." (PMID 36672844, 2022). "JAK2 and JAK3 are expressed in epithelial and hematopoietic cells, and their deficiency results in hematological disorders, including immunodeficiency." (PMID 38990897, 2024). "As immune function depends on the presence of these lymphoid cells, this data suggests that intermittent dosing could minimize immunodeficiencies induced by treatment with a JAK2 inhibitor." (PMID 22623993, 2012).